IL6 (interleukin 6)
Diseases named in the same sentence as IL6 in open-access papers (continued):
Sharing a sentence is not in itself a finding about the gene and the disease.
anemia (continued). "Moreover, the correlation with IL-6 was very strong in patients with anemia who were also more active." (PMID 35620179, 2022). "Whether inhibition of IL-6-mediated inflammation in the early phases of pulmonary TB would be beneficial to correct anemia and support chemotherapy remains to be determined." (PMID 36014824, 2022). "Importantly, IL-6 is a facilitator of cancer anorexia and the primary inducer of cancer anemia, and both states inhibit the mTOR axis, resulting in a vicious loop that accelerates muscle wasting." (PMID 35159388, 2022). "Another report showed a strong correlation of serum IL-6 and hepcidin in patients with anemia of chronic disease, but not in patients with iron deficiency anemia." (PMID 36014824, 2022). "Anemia can occur in heart failure with or without chronic kidney disease and is likely to be due to increased production of tumor necrosis factor-alfa and interleukin-6, which in turn can cause reduced erythropoietin secretion." (PMID 34978627, 2022). "Our results suggest that the blockade of IL-6 receptor by sarilumab improves the hemoglobin level, possibly via decreasing hepcidin levels, and may contribute to the greater improvement in anemia observed with IL-6 inhibitors." (PMID 36008838, 2022). "Alternatively, cytokines such as IL-6, IL-1 and TNF-alpha and metabolites associated with anemia of chronic disease could modulate monocyte function and lead to an upregulation of PD-1." (PMID 35625643, 2022). "Moreover, the results revealing a divergent effect of co-infection with the increased balance between pro-and anti-inflammatory cytokines and reduced IL-6 levels but increases the anemia occurrence." (PMID 35749690, 2022). "IL-6 is actively involved in the pathology of anemia of patients with TAK." (PMID 34750666, 2022). "Chronic inflammation seems to be the primary cause of anemia in pulmonary TB patients and appears to be driven by elevated systemic levels of IL-6, but not IFN-γ." (PMID 36014824, 2022). "Frailty was also associated with a low-grade chronic pro-inflammatory state characterised by increased levels of CRP and IL-6, and could further result in anaemia." (PMID 35172806, 2022). "Furthermore, when we compared hepcidin and cytokines levels in anaemia and non-anaemia women, we discovered statistically significant differences in hepcidin and IL-6 concentrations." (PMID 36612220, 2022). "However, there were gender differences regarding inflammatory parameters and anemia: higher neopterin, hsCRP and IL-6 concentrations were positively related to anemia severity especially in men, while IL-12 rose with anemia severity especially in women." (PMID 34458328, 2021). "Importantly, IL-6 is considered a mediator of cancer anorexia and the main inducer of cancer anemia, and both conditions eventually inhibit the mTOR axis, thereby establishing a vicious cycle that augments muscle wasting." (PMID 33809200, 2021). "Furthermore, treatment with LDN-193189, noggin and ALK3-Fc (BMP antagonists) can inhibit IL-6-induced hepcidin expression, leading to improved turpentine-induced anemia." (PMID 34679725, 2021). "In the group with elevated IL-6, anemia was more frequent (52% vs. 25%; p = 0.014)." (PMID 33535417, 2021). "In CD, cytokines, such as interleukin-6 (IL-6), which are directly involved in the pathogenesis of the disease, inhibit the albumin promoter and induce hypoalbuminemia or act on the iron metabolism, resulting in anemia." (PMID 34575326, 2021). "Firstly, ferritin and IL-6 levels did not change during treatment, which excludes iron deficiency and anemia due to inflammation; in addition, most iron measurements were within the normal range." (PMID 34202704, 2021). "Hepatocytes respond to IL-6 by diminishing albumin production and producing several acute phase proteins and hepcidin, which in turn leads to reduced intestinal iron absorption, impaired release of iron stored in the macrophages, and anemia." (PMID 33777463, 2021).
anemia (continued). "Further, α+-thalassemia, sTfR and the cytokine balance (involving TNF-RI, TNF-RII, and IL-6) of the newborn were related to fetal anemia, but these relationships were limited to offspring of iron-deficient mothers in whom all but thalassemia were modified by parity." (PMID 33995348, 2021). "It is possible that the main contributors to anemia may be proinflammatory cytokines such as interleukin 6 (IL-6) and tumor necrosis factor α (TNF-α)." (PMID 34071554, 2021). "Studies to examine IL-6 and hepcidin for their interrelationships to fetal anemia are warranted." (PMID 33995348, 2021). "TNF-α contributes to anemia by inhibiting erythropoietin secretion and/or through direct toxicity on erythroid precursor cells, while interleukin-6 induces the production of hepcidin, which binds to ferroportin, thereby blocking the intestinal absorption of iron." (PMID 34071554, 2021). "On the contrary, patients treated with an anti-TNF antibody or an anti-IL-6 antibodies exhibit reduced levels of inflammatory markers such as IL-6, hepcidin, and/or C-reactive protein, correlating with improvement in anemia related to autoimmune inflammatory conditions." (PMID 33842333, 2021). "In addition to high iron levels, inflammatory signaling molecules such as interleukin-6 (IL-6) will increase the production of hepcidin, while conditions of anemia and hypoxia, increased erythropoiesis and testosterone will inhibit the pathway." (PMID 34373750, 2021). "As already outlined by Locatelli’s group, the improvement in anemia is usually accompanied with a decrease in IL-6 level, suggesting that the use of VEM may have a beneficial effect on anemia indices." (PMID 32471186, 2020). "We finally provide preliminary evidence that lignans could ameliorate inflammation and anemia in CeD, showing that lignans could inhibit the local expression of Interleukin-6 (IL-6) and hepcidin, the main regulator of iron homeostasis." (PMID 32349426, 2020). "Some inflammatory cytokines, such as tumor necrosis alpha (TNF-α) and interleukin (IL-6), were reported to inhibit the maturation of erythrocytes through suppression of hematopoietic system in the marrow, resulting in anemia after hematopoietic stem cell transplantation." (PMID 33537231, 2020). "Iron utilisation barrier induced by IL-6 plays an important role in RA-related anaemia." (PMID 33198544, 2020). "Notably, patients suffering from anemia demonstrated significantly higher IL6 (p = 0.009) and CRP (p = 0.031) concentrations as compared to non-anemic patients." (PMID 33087116, 2020). "Increased hepcidin production stimulated by IL-6 enhances iron retention in reticuloendothelial cells and impairs iron release, thus represses intestinal iron absorption and reduces erythropoiesis leading to anemia." (PMID 32095285, 2020). "Moreover, IL6 plays a role in the development of anemia of chronic kidney disease in children (CKD anemia)." (PMID 32665031, 2020). "Elevated IL-6 levels have been observed in field studies of children with severe malaria anaemia and IL-6 may be upregulated when hepcidin levels are low further inhibiting neutrophil influx." (PMID 32972031, 2020). "The proposed IL-6-ERRγ-BMP6 pathway is probably active in inflammatory conditions when pro-inflammatory cytokines, including IL-6, levels are increased and may up-regulate hepcidin expression, leading to hypoferremia and anemia, such as in inflammatory anemia." (PMID 32998264, 2020). "Subsequently, chronic inflammation can lead to anemia through several pathways, e.g., induction of the master regulator of iron homeostasis hepcidin by Interleukin-6 or the inhibition of erythropoietin formation in the kidney mediated by Interleukin-1 and TNF-alpha." (PMID 32903529, 2020). "The increased cytokines (TNF-α, IFN-γ, IL-1 and IL-6) not only directly promote the development of RA, but also inhibit differentiation and proliferation of erythroid progenitor cells, result in the blunt response of erythropoietin to anaemia." (PMID 33198544, 2020).
anemia (continued). "Consistent with other's findings, the initial rise of IL6, followed by an increase of IL-12p70 and moderate changes in TNF-α and MCP-1 that are temporally associated with anemia, may play a role in its etiology." (PMID 33013831, 2020). "However, it seems that blocking hepcidin through manipulation of the IL-6 signaling cascade is feasible for the treatment of cancer anemia." (PMID 30641920, 2019). "• Loss of lean tissue mass, with a weight loss >5% of body weight in 12 months; Or• BMI lower than 20, plus three of the following: decreased muscle strength, fatigue, anorexia, low fat-free mass index, increase of inflammation markers such as CRP or IL-6, anemia, and low serum albumin." (PMID 31681777, 2019). "For example, anemia was significantly worse in the KDSS patients which might be a result of IL-6 induced up-regulation of hepcidin." (PMID 30611297, 2019). "With consistently elevated IL-6, hypoalbuminemia, hyponatremia and anemia appeared in patients." (PMID 30611297, 2019). "CRP has been associated to paraneoplastic symptoms and cachexia, leading to an understanding of a condition with chronic elevated IL-6 in cancer which leads to anemia, elevated CRP levels and a change in the gut microbiota that possibly increases the gut permeability further worsening the cachexia." (PMID 30038723, 2018). "Anaemia of chronic disease (as suggested by high serum IL-6) may also contribute to the moderate anaemia seen in our cohort; hepcidin measurements would help to clarify this." (PMID 30046137, 2018). "Tocilizumab might be an effective treatment for RA with MDS, especially in those with high levels of IL-6, elevated C-reactive protein, and severe anemia." (PMID 29924032, 2018). "There was a correlation between the plasma concentrations of ferritin and IL-6, suggesting that the iron status of PD patients with high plasma ferritin may reflect the anaemia of chronic disease." (PMID 28469157, 2017). "Sometimes, however, anemia can persist in HIV-chronically-infected patients, even after HIV replication was suppressed with cART, and it has been associated with elevated levels of IL-6, CRP and D-dimer and with monocyte activation." (PMID 29258550, 2017). "To further investigate the anemia observed in the LC-06-JCK–bearing mice reported in our previous study, we first confirmed the reproducibility of our established experimental model in terms of development of anemia and production of human IL-6 from the xenograft." (PMID 27068103, 2016). "A mechanism linking cancer-related anemia and IL-6 through hepcidin production is suggested." (PMID 27068103, 2016). "In this study, we further investigated iron metabolism to assess whether the blockade of IL-6 signaling could prevent anemia in this IL-6–overproducing xenograft model." (PMID 27068103, 2016). "IL6 is an important proinflammatory cytokine of RA that is involved in leukocyte activation, antibody production, and some systemic symptoms, such as asthenia, acute-phase mediator response, and anemia." (PMID 27642302, 2016). "This hypothesis provides a rationale for therapeutic targeting of IL-6 signaling pathways for managing anemia in cancer patients." (PMID 27068103, 2016). "In the CRF rats, despite the increased EPO serum levels, anemia persisted and was linked to low serum iron and transferrin levels, while serum IL-6 and hsCRP levels showed the absence of systemic inflammation." (PMID 26712750, 2015). "IL-6 can induce hepcidin synthesis, which leads to iron-restricted erythropoiesis and anemia." (PMID 25822717, 2015). "The anemia and hypoferremia were reversible after cessation of IL-6." (PMID 24576354, 2014). "With this in mind, the new therapeutic anti-IL-6 strategies tested in clinical trials in patients with Crohn’s disease may be of special interest also for anemia of chronic diseases in IBD." (PMID 25646159, 2014). "Further studies will be necessary to fully determine the role of IL-6 in anemia of RA." (PMID 24878740, 2014).
anemia (continued). "Siltuximab, an anti-IL6 monoclonal antibody drug used in clinic, was shown to be effective in reducing hepcidin expression in patients with Castleman’s disease (CD) and in improving their anemia." (PMID 24808863, 2014). "hepcidin, a small cysteine-rich cationic peptide with antibacterial activity, secreted predominantly from hepatocytes whose expression is regulated positively by body iron load/stores and inflammatory signals, chiefly IL-6, and suppressed by hypoxia and anemia." (PMID 24069586, 2013). "Hepcidin is increased by iron loading and IL-6 and decreased by anemia or hypoxia." (PMID 24649250, 2013). "Proinflammatory cytokines, particularly tumor necrosis factor α (TNF-α), interleukin 6 (IL-6) and IL-1 play important roles in the pathogenesis of RA and are thought to contribute to the development of RA-anemia by modulating iron metabolism and suppressing bone marrow erythropoiesis." (PMID 24286116, 2013). "Though recent studies have found that an increase in serum hepcidin in active RA patients was associated with elevated serum IL-6 and TNF-α levels, the role of hepcidin and its regulation by cytokines in the pathogenesis of RA-anemia is still largely unknown." (PMID 24286116, 2013). "IL-6 impairs iron utilization, leading to anemia of chronic disease." (PMID 23140401, 2012). "Hepcidin is also reported to be upregulated in MM patients by IL-6-dependent and -independent mechanisms, and may play a role in the development of anemia." (PMID 23170109, 2012). "The hepatic IL-6/STAT3 signal has a role in anemia of inflammation in vivo." (PMID 23170109, 2012). "Ang-2 sensitization of endothelial cells to TNF may amplify secretion of endothelial cytokines, such as IL-6, that can promote anemia." (PMID 21364762, 2011). "In addition, recent data shows a correlation between elevated TNF-α, IL-6 and IL-8 levels and anemia in patients with chronic kidney disease." (PMID 20169072, 2010). "It is worth noting that inhibition of the BMP signalling pathway, which drives hepcidin transcription, impairs its IL‐6‐mediated induction and may therefore represent a potential therapeutic target for modulating this pathway in cases of anaemia of inflammation." (PMID 40637365, 2025). "Furthermore, it was found that cancer-related anemia may result from erythropoietin inhibition, facilitating the suppression of erythropoiesis by cytokines (IL-6, TNF-α)." (PMID 39372868, 2024). "Besides, elevated serum IL‐6 indicates 5‐FU‐induced anemia is accompanied by inflammation." (PMID 38243847, 2024). "Indeed, IL-6 is the key cytokine involved in the pathogenesis of cachexia-related changes in energy metabolism, nutritional status, and body composition, as well as related signs and symptoms such as anorexia, anemia, and fatigue." (PMID 36831431, 2023). "It is currently unclear whether IL-6 has a role in promoting this process or facilitates unrelated or protective mechanisms, and as such its role in the development of anemia through oxidative damage of RBCs during canine babesiosis is unclear and further investigation is required." (PMID 36839438, 2023). "The other hypothesis for anemia secondary to infection is linked to effects of various cytokine mediators of inflammation, such as tumor necrosis factor (TNF), interleukin (IL-1 and IL-6), and the interferons (IFNs)-IFNγ." (PMID 38042804, 2023). "Anemia due to a chronic disease, such as cancer, results from the dysregulation of iron homeostasis induced by inflammatory cytokines such as interleukin-6 (IL-6) and interferon gamma (IFN-γ) as well as the suppression of erythropoietic activity, and it associates with poor OS among cancer patients." (PMID 38049762, 2023). "In severe P. falciparum malaria with corresponding high parasite density, a more intense pro-inflammatory environment with an elevation of cytokines including TNF-alpha, IL-1 and IL-6 may be created and this could contribute to the delayed erythrocytic response seen in P. falciparum induced anaemia." (PMID 36989322, 2023).
anemia (continued). "IL-6 stimulates the production of hepcidin which is the main iron-regulatory hormone preventing absorption of iron from the intestines and release from macrophages leading to low iron levels which may result to anaemia." (PMID 37507740, 2023). "Hence, the proposed mechanism suggests that iron deficiency anemia might indirectly regulate LRG1 expression, possibly by upregulating HIF-1α expression, which regulates direct targets of LRG1 promoter including IL-6 and TNFα." (PMID 37513518, 2023). "Thus, it can be concluded that serum IL-6 levels may be an important factor playing a role in the pathogenesis of anemia in SLE patients." (PMID 37371554, 2023). "It was surprising that IL-6, called “a cytokine for gerontologists”, showed poor diagnostic usefulness to distinguish the individuals with anemia from no-anemia ones (AUC = 0.523, sensitivity 62.2%, specificity 51.1%, OR = 1.939, 95%Cl 0.848–4.489) compared to other cytokines." (PMID 37240288, 2023). "Here, in a post hoc analysis, we describe the association of anemia and blood Hb levels to the clinical TB score and select baseline variables including BMI, MUAC, vitD3, ESR, CD4, and CD8 T cell counts, as well as systemic levels of the T-cell-produced Th1 cytokine IFN-γ and pro-inflammatory IL-6." (PMID 36014824, 2022). "IL-6 can act as an activator or inhibitor of T-cell responses, depending on the duration of its activity; moreover, by inducing systemically specific derangements of energy metabolism, nutritional status, and symptoms as anemia and anorexia, it significantly negatively affects T-cell functions." (PMID 35742933, 2022). "Maternal anemia was the strongest predictor for prematurity in association with SARS-CoV-2 infection (β = 3.65, CI = 1.46–5.39, p-value < 0.001), followed by elevated CRP (β = 2.11, CI = 1.20–3.06, p-value < 0.001), and respectively IL-6 (β = 1.92, CI = 1.20–2.47, p-value = 0.001." (PMID 36579593, 2022). "Furthermore, recent results obtained by suggest that elevated IL-6, an important component of the cytokine storm, could result in progressive anemia." (PMID 35355599, 2022). "IL-6 has also been shown to affect lipid metabolism by stimulating hepatic fatty-acid synthesis and adipose-tissue lipolysis to increase cholesterol synthesis while decreasing cholesterol secretion, and to be related to the anemia or osteoporosis that accompanies RA." (PMID 36676031, 2022). "Aging is also associated with a chronic inflammatory phenotype that has been characterized by anemia, immunosenescense, and thrombocytosis, as well as overproduction of the inflammatory cytokines interleukin-1 (IL-1), tumor necrosis factorα (TNFα), and interleukin-6 (IL-6)." (PMID 34502021, 2021). "Besides anaemia, other hematologic laboratory abnormalities including leucocytosis and thrombocytosis may develop due to overproduction of IL-6." (PMID 33715142, 2021). "Increased circulating hepcidin and sTfR, possibly secondary to increased pro-inflammatory C-reactive protein (CRP) and IL-6, might result in reduced iron release in the bloodstream, which triggers uncompensated anemia, much like in chronically diseased patients." (PMID 34573092, 2021). "HHV8+ MCD is a waxing and waning febrile illness, commonly occurring in immunocompromised populations (e.g. HIV+), characterized by diffuse lymphadenopathy, splenomegaly, and anemia. iMCD does not have a known pathogenesis, however, it is associated with high levels of IL-6." (PMID 34527461, 2021). "However, in none of our patients, serum IL6, that upregulates Hepcidin, was tested even if iron deficiency related to Hepcidin increase in “inflammaging” is implicated not only in anemia but also in other age-associated conditions." (PMID 32235484, 2020).